PIK3CA (phosphatidylinositol-4,5-bisphosphate 3-kinase catalytic subunit alpha)
Diseases named in the same sentence as PIK3CA in open-access papers (continued):
Sharing a sentence is not in itself a finding about the gene and the disease.
ovarian carcinoma (continued). "PIK3CA and KRAS mutations in ctDNA serve as prognostic markers and indicate outcomes in epithelial ovarian cancer patients." (PMID 37629546, 2023). "In Xiaoqing Wang’s work, the proliferation and migration of ovarian cancer cells were inhibited by dihydrotanshinone I via transcriptional repression of the PIK3CA gene." (PMID 35744840, 2022). "In PIK3CA-mutated ovarian cancer cells, BKM120 cooperated with Olaparib, in part through downregulation of BRCA1, with similar results observed in PIK3CA-wild type cells." (PMID 35205643, 2022). "PIK3CA gene amplification is frequent in gastric carcinoma (36.4%), thyroid adenocarcinoma (30%), prostatic cancer (28%), ovarian cancer (13.3–29.8%), and cervical carcinoma (9.0–80%)." (PMID 36539659, 2022). "The PI3K/AKT/mTOR and the RAS/RAF/MEK/ERK kinase signaling pathways are attractive targets for potential therapeutic inhibitors, due to the high frequency of mutations to PTEN, PIK3CA, KRAS and BRAF in several ovarian cancer subtypes." (PMID 35053555, 2022). "Through exome sequencing, it was observed that 79% of the lesions (EC and/or DIE) had mutations, and 26% of these were found in the ARID1A, PIK3CA, KRAS, and PPP2R1A genes, where PIK3CA and KRAS are genes frequently mutated in ovarian cancer." (PMID 35807280, 2022). "In vitro buparlisib has been tested in combination with the PARP inhibitor olaparib and shown to effectively inhibit proliferation, survival and invasion in the PIK3CA mutant ovarian cancer cell lines SKOV-3, IGROV-1, and HEYA-8." (PMID 35582310, 2021). "MiR-337-3p is a tumor inhibitor in several human cancers; it reduced ovarian cancer cell growth by regulating PIK3CA and PIK3CB." (PMID 33896365, 2021). "Meanwhile, copy number gains of PIK3CA and PIK3R4 were associated with decreased survival in ovarian cancer." (PMID 31472672, 2019). "In ovarian cancer, TERT promoter mutation and PIK3CA mutation are considered mutually exclusive, whereas this coexistence is reported in other carcinomas." (PMID 29222734, 2018). "MYC and RB1 had the highest frequency of copy number variations (6/21, 29%) in recurrent ovarian cancers, followed by PIK3CA (3/21, 14%)." (PMID 29797793, 2018). "Together these data suggest that the deletion of ARID1A and mutation in Pik3ca*H1057R results in increased IL6 expression leading to the ovarian surface epithelial hyperplasia and eventually clear cell ovarian cancer." (PMID 30087267, 2018). "The ovarian cancer cell lines SKOV3, OC 316, A2780, UPN-251, and OVCAR-3 have all been shown to possess PIK3CA mutations or copy number gain, which cause the constitutive activation of AKT." (PMID 28152500, 2017). "Till date NF-κB’s role as a positive regulator for PIK3CA promoter in ovarian cancer cells by TNFα is known." (PMID 29169370, 2017). "CA125 responses were also observed in three patients with ovarian cancer including one with known high PIK3CA gene copy number." (PMID 28008141, 2017).
ovarian carcinoma (continued). "On the contrary, PIK3CA mutation favors malignant progression in head and neck squamous cell carcinoma, and poor prognosis in ovarian cancer, whereas PIK3CA amplification predicts reduced survival in gastric cancer." (PMID 28060766, 2017). "To date, few investigations have found a relationship between the effect of 5-AZ and PIK3CA methylation in ovarian cancer, especially with the invadopodia-promoting function of PI3K." (PMID 28947962, 2017). "In a phase I trial with GDC-0941, a heavily treated ovarian cancer patient with PIK3CA amplification experienced disease stabilization for 4 months with significant pharmacodynamic changes." (PMID 27016421, 2016). "The coexistence of PIK3CA and KRAS mutations has been shown in several different tumors types including lung, colorectal, pancreatic and ovarian cancer." (PMID 26968814, 2016). "In a phase I trial of GDC-0941, a heavily treated ovarian cancer patient with PIK3CA amplification achieved disease stabilization for 4 months with significant pharmacodynamic changes." (PMID 27095573, 2016). "This is consistent with observations reported in colon, gastric and ovarian cancer cell types, and with our previous data on the effects of expression of mutant PIK3CA in TERT-NHUC and in other cell types." (PMID 27465249, 2016). "For ovarian cancer, KRAS is the most frequently mutated gene (18%), whereas PIK3CA is mostly affected in cervical cancer (24%) and PTEN in endometrial cancer (39%)." (PMID 24671188, 2014). "Invasion of ovarian cancer cells is reduced with AKT1 knockout but to a lesser extent then PIK3CA knockout." (PMID 23591839, 2013). "Although mutations in PIK3CA, KRAS, PTEN, BRAF and ARID1A are uncommon in HGSOC, they are characteristic of other ovarian cancer subtypes." (PMID 23839242, 2013). "In ovarian cancers PI3K activation, occurring via either PIK3CA gene amplification/mutations or PTEN protein loss, has been reported by several studies with the highest frequency in most malignant histotypes." (PMID 22927847, 2012). "GDC0941, a PI3kinase inhibitor, has also demonstrated activity in ovarian cancer specifically in situations of PIK3CA amplification." (PMID 21931712, 2011). "Genetic amplification of PIK3CA, which encodes p110α catalytic subunit of PI3K (Class IA catalytic subunit) have been observed in approximately 40% of ovarian cancers." (PMID 24281034, 2010). "To further confirm PIK3CA is indeed expressed in early-stage ovarian cancer, we also examined the protein product of PIK3CA gene, p110α, by immunohistochemical staining in early malignant transformed human ovarian surface epithelium." (PMID 19172191, 2009). "Next, we examined mRNA expression of PIK3CA in microdissected normal human ovarian epithelium (n = 4) as well as epithelial ovarian cancer specimens including FIGO stages I (n = 16), II (n = 8), III (n = 31) and IV (n = 11)." (PMID 19172191, 2009). "To demonstrate that our transgenic construct was able to constitutively activate PI3-kinase pathway, we transient transfected myr-PIK3CA, wt-PIK3CA and control vectors to ovarian cancer cell line 2008." (PMID 19172191, 2009). "Our in vivo data suggests that PIK3CA activation is one of the early genetic events in ovarian cancer." (PMID 19172191, 2009). "Previous studies on the function of PIK3CA in ovarian cancers have been predominantly focused on the maintenance and survival of late-stage of ovarian carcinoma." (PMID 19172191, 2009). "To confirm our previous finding, we first compared expression levels of PIK3CA mRNA in established epithelial ovarian cancer cell lines (n = 15) with primary cultures of immortalized human ovarian surface epitheliums (IOSEs, n = 6)." (PMID 19172191, 2009).
ovarian carcinoma (continued). "In this study, we examined the expression of PIK3CA in vivo and its relationship with the tumor microenvironment in human ovarian cancer." (PMID 18335034, 2008). "To reveal spatial aspects of PIK3CA regulation in tumor in vivo, we first examined the expression of p110α in human ovarian cancer specimens." (PMID 18335034, 2008). "Collectively, these data strongly indicate that PIK3CA supports ovarian cancer growth through multiple and independent pathways affecting cell proliferation, apoptosis and angiogenesis, and plays an important role in ovarian cancer progression." (PMID 19384426, 2007). "In a subsequent study, PIK3CA mRNA was detected in 66.6% of stage I and 93.9% of advanced stage ovarian cancer specimens and in all ovarian cancer cell lines." (PMID 19384426, 2007). "The increased copy number of the PIK3CA gene is associated with increased PIK3CA transcription, P110-alpha protein expression, and PI3K activity in ovarian cancer." (PMID 16168105, 2005). "Copy number increases of chromosome 3q in ovarian carcinomas have previously been reported and mapped to a region at 3q26 containing PIK3CA." (PMID 12771925, 2003). "The inactivation of PTEN may also play a role in mediating resistance to PI3K inhibition as long as PTEN and PIK3CA alterations co-occur in some ovarian carcinoma patients." (PMID 38391958, 2024). "This discovery suggests that therapeutic intervention with specific kinase inhibitors might enhance chemotherapy sensitivity in ovarian carcinomas with PIK3CA amplification." (PMID 38391958, 2024). "Some evidence shows that only the combined use of PIK3CA inhibitor (BKM120) and PARP inhibitor (olaparib) may prove effective in treating ovarian cancers with a wider range of cancer-associated genetic alterations." (PMID 38391958, 2024). "However, PTEN (3%), PIK3CA (3%) and ARIDA (3%) mutations have all been reported in Type II serous ovarian carcinomas, they are just more frequent in Type I ovarian cancers." (PMID 38940864, 2024). "When looking across all ovarian cancer subtypes genes involved in the PI3K–Akt pathway (PTEN and PIK3CA), genes associated with the MAPK pathway (KRAS and BRAF), and other oncogenic genes (CTNNB1 and PPP2R1A) were also found to be mutated at a moderate frequency." (PMID 35740550, 2022). "Dihydrotanshinone I could inhibit ovarian cancer cell proliferation and migration by transcriptional repression of the PIK3CA gene." (PMID 35744840, 2022).
ovarian carcinoma (continued). "Moreover, driver mutations in PIK3CA, KRAS, and ARID1A have been found in the epithelium of ovarian and extra-ovarian endometriosis tissues and ovarian cancers associated with endometriosis." (PMID 35740424, 2022). "To exemplify the power of NeDRex to extract biologically meaningful pathways from starting seeds, we used the ovarian cancer (OC) associated genes from NeDRexDB (AKT1, ALPK2, CDH1, CTNNB1, EPHB1, OPCML, PIK3CA, PRKN) and constructed disease module using the MuST algorithm." (PMID 34824199, 2021). "Interestingly, the mutation rates for commonly reported genes in ovarian cancer such as RB1, PTEN, PIK3CA, NRAS, KRAS, and BRAF were below 3% in the entire cohort." (PMID 33016563, 2021). "We searched for data on PIK3CA mutations in noncancerous sites in ovarian cancer from previous reports." (PMID 34172890, 2021). "Some studies have described a spatial and chronological association with transformation of atypical endometriosis to ovarian cancer and, molecular studies have detected similar genetic alterations (e.g. mutations of ARID1A and PIK3CA) in endometriosis and in ovarian cancer of clear cell histology." (PMID 34185779, 2021). "Next, we investigated whether DHTS inhibits ovarian cancer cell migration and invasion by regulating PIK3CA transcription." (PMID 32860347, 2020). "Genetic mutations in PTEN along with alterations of PIK3CA, PIK3R1, ARID1A, Wnt/β-catenin, microsatellite instability, SRC, and KRAS have been demonstrated to be critical in the pathogenesis of endometriosis-associated ovarian cancers." (PMID 31731647, 2019). "However, AKT phosphorylation levels were significantly higher in uterine cancer than in breast or ovarian cancer, consistent with the high frequency of PTEN loss and PIK3CA activating mutations in uterine cancer lines." (PMID 30012111, 2018). "Studies examining endometriotic lesions and ovarian cancer from the same patient have shown concordant mutations in ARID1A, phosphatase and tensin homolog (PTEN), PIK3CA, and KRAS, suggesting that mutations in endometriosis cause a predisposition to ovarian cancer." (PMID 30087267, 2018). "The use of inhibitors of methylation could, at least in some cases, stimulate the invasive growth or metastasis of ovarian cancer though reactivation of PIK3CA genes that are silenced by promoter methylation." (PMID 28947962, 2017). "Thus, consistent with its inhibitory effect on cell proliferation, the PI3K inhibitor BKM120 treatment resulted in attenuated PI3K/AKT/mTOR signaling in PIK3CA mutant ovarian cancer cells." (PMID 26909613, 2016). "Particularly, amplification or mutations of PIK3CA (encoding the catalytic subunit of PI3K P110α), loss of PTEN, and deregulation of AKT are well-known mechanisms that activate this pathway in approximately 70% of ovarian cancers." (PMID 26325371, 2015). "However, limited as models of HGSOC, these cell lines do have a utility as general models of ovarian cancer, for example SKOV3 is a good model of AKT-driven ovarian cancer, harboring an activating point mutation in PIK3CA." (PMID 24860781, 2014). "There have been reports showed that PIK3CA gene was happened to CNVs in ovarian cancer, cervical cancer, and gastric cancer; and that CNVs in PIK3CA were reported to be an independent factor for predicting poor OS of patients with ovarian cancers and gastric cancers." (PMID 24418330, 2014). "However, the effect of the common therapeutic drugs (cisplatin and paclitaxel) on this PIK3CA promoter in ovarian cancer cells still remains to be investigated." (PMID 23393606, 2013).
ovarian carcinoma (continued). "Previous studies have analysed PIK3CA gene mutation in NSCLC and have demonstrated that its frequency is relatively low (3.4–4.3%) compared to that observed in other tumours, such as breast, colon and ovarian cancers." (PMID 22949056, 2012). "In addition, we analyzed associations between exon 9 PIK3CA and KRAS mutations and between exon 20 PIK3CA and KRAS mutations in colorectal and ovarian cancers, which were the two largest disease subgroups." (PMID 21829508, 2011). "On the other hand, our study demonstrated PIK3CA amplification in ovarian tumors, with a relatively high frequency (35.5%), which suggests the major role of PIK3CA amplification in the activation of these ovarian cancers." (PMID 19638206, 2009). "Our previous studies indicate that mRNA expression of PIK3CA is significantly up-regulated in the early-stage of ovarian cancer development, strongly suggesting that PIK3CA might be involved in OSE transformation." (PMID 19172191, 2009). "Genetic alterations of its catalytic subunit alpha, PIK3CA, have been identified in ovarian cancer." (PMID 19172191, 2009). "In addition, increasing evidence indicates that PIK3CA is activated in a large percentage of human ovarian cancer patients." (PMID 19172191, 2009). "Several studies have showed PIK3CA gene amplification in ovarian cancers." (PMID 19638206, 2009). "In many human tumors, including epithelial ovarian cancer, PIK3CA activation is a critical oncogenic event and can be mediated by multiple genetic/genomic alterations such as gene copy number amplification, gain of functional mutations, and transcriptional up-regulation." (PMID 19172191, 2009). "Taken together, our results indicate that inflammation triggered in response to tumor cell death might one of the mechanisms that upregulate PIK3CA expression via NF-κB in ovarian cancer cells in vivo." (PMID 18335034, 2008). "In vitro, PIK3CA expression positively correlated with the expression of VEGF in ovarian cancer cells, whereas LY294002 reduced both the constitutive and inducible expression of HIF-1α at the mRNA and protein levels and abrogated VEGF up-regulation by glucose starvation." (PMID 19384426, 2007). "Endometrioid ovarian carcinomas show broad morphological similarities to their endometrial counterparts with the most common molecular alterations in endometrioid OC including mutations in CTNNB1 (31–53.3%), PIK3CA (15–40%), ARID1A (30%), and PPP2R1A (7–16.6%)." (PMID 41153668, 2025). "Multiple preclinical studies have shown these synergistic antitumor activities of dual blocking of PI3K and PARP in breast cancer, prostate cancer, and ovarian cancer regardless of PIK3CA or BRCA mutational status, which broadens the indications of PARP inhibitors." (PMID 36533385, 2023). "The reason for the presence of PIK3CA mutations in Pap smear samples from ovarian cancer cases without PIK3CA mutations in the tumor may be that PIK3CA mutations are more likely to occur in the cervix in ovarian cancer cases." (PMID 34172890, 2021).